RNU6-1123P (RNA, U6 small nuclear 1123, pseudogene)
Gene: Small nuclear RNA gene on chromosome 11 (119,656,311 to 119,656,416, forward strand). Ensembl gene ENSG00000199217.
Homologues: Orthologues: chimpanzee U6 (99% identical), macaque U6 (92% identical), guinea pig U6 (87% identical), pig U6 (76% identical). Paralogues in human: RNU6-797P (89% identical), RNU6-1047P (88% identical), RNU6-115P (88% identical), RNU6-1094P (87% identical), RNU6-1243P (87% identical), RNU6-41P (87% identical), RNU6-1159P (86% identical), RNU6-11P (86% identical), RNU6-208P (86% identical), RNU6-379P (86% identical), RNU6-37P (86% identical), RNU6-454P (86% identical), and 1288 more.